FHL2 (four and a half LIM domains 2)
Diseases named in the same sentence as FHL2 in open-access papers (continued):
Sharing a sentence is not in itself a finding about the gene and the disease.
Obesity (4 papers, 2022 to 2026). Accumulation of substantial excess body fat. "A most recent study indicated that FHL2 also affects fat metabolism because FHL2 deficiency in mice reduced high-fat diet-induced obesity, but the underlying molecular mechanisms remained unsolved." (PMID 37834391, 2023). "In order to elucidate the role of FHL2 in obesity, wild-type (wt) and FHL2-deficient (FHL2KO) mice were fed with a Western-type diet (WTD) for 18 weeks." (PMID 37834391, 2023). "This is interesting as we recently elucidated the protective role of FHL2 deficiency against developing obesity in mice and highlighted the association between FHL2 expression and browning of white adipose tissue in humans." (PMID 36901761, 2023). "We recently reported a novel role for FHL2 in the context of energy metabolism, as FHL2 deficiency protects mice from developing diet-induced obesity." (PMID 35802167, 2022). "Additionally, FHL2 is expressed in different types of cancer; recently, we demonstrated that FHL2 deficiency protects mice from diet-induced obesity." (PMID 35802167, 2022). "Thus, in search for the molecular mechanisms through which FHL2 deficiency protects from diet-induced obesity, we focused our attention on macrophages, which we identified as the main cellular source of the enhanced FHL2 expression in the VAT of obese mice and humans." (PMID 37834391, 2023). "Together, these results reveal the upregulation of FHL2 in the VAT of mice with WTD-induced obesity, as well as in the VAT of obese men, and indicate macrophages as the main cellular source of enhanced FHL2 expression." (PMID 37834391, 2023). "In this study, we newly found enhanced FHL2 expression in macrophages in visceral adipose tissue (VAT) of mice with Western-type diet-induced obesity and obese humans." (PMID 37834391, 2023). "In this study, we aimed to gain new insights into the expression and functional role of FHL2 in VAT in diet-induced obesity." (PMID 37834391, 2023). "We found enhanced FHL2 expression in the VAT of mice with Western-type diet (WTD)-induced obesity and obese humans and identified macrophages as the cellular source of enhanced FHL2 expression in VAT." (PMID 37834391, 2023). "Studies with cell-type specific FHL2 depletion are required to unravel the complex role of FHL2 in different tissues as well as their quantitative effects on the development of obesity and its comorbidities." (PMID 37834391, 2023). "Collectively, these findings indicate that FHL2 is a positive regulator of NPY and MCP-1 expression in macrophages and herewith closely linked to the mechanism of obesity-associated lipid accumulation and inflammation in VAT." (PMID 37834391, 2023). "We found enhanced FHL2 expression in visceral adipose tissue (VAT) of mice with Western-type diet (WTD)-induced obesity and obese humans." (PMID 37834391, 2023). "In this study, we aimed to gain new insights into the expression and the functional role of FHL2 in adipose tissue and obesity." (PMID 37834391, 2023). "Collectively, our findings indicate that FHL2, as a positive regulator of NPY and MCP-1, is closely linked to the mechanism of obesity-associated lipid accumulation and inflammation in VAT." (PMID 37834391, 2023). "Thus, FHL2 appears as a potential novel target to interfere with the macrophage–adipocyte crosstalk in VAT for treating obesity and related metabolic disorders." (PMID 37834391, 2023). "Still, in combination with our supporting in vitro data, we would like to suggest a critical role of FHL2 in the crosstalk between macrophages and adipocytes in the VAT during diet-induced obesity." (PMID 37834391, 2023).
viral infection (4 papers, 2018 to 2025). "Previous studies have shown that FHL2 is a key regulator of immune response in virus infection, and it can regulate IFN-β to inhibit virus replication." (PMID 39858856, 2025). "IRF-3 is indispensable for IFN-β production upon viral infection, further emphasizing the significant role of FHL2 in regulating IFN-β responses." (PMID 38203523, 2023). "HLH in these patients could be either EBV-driven HLH, secondary HLH or genetic forms of FHL other than FHL2 triggered by infection as none of patients with PRF1 gene mutation in our study were positive for viral infection." (PMID 33224420, 2020).
acute myeloid leukemia (3 papers, 2017 to 2021). Acute myeloid leukemia (AML) is a group of neoplasms arising from precursor cells committed to the myeloid cell-line differentiation. "One GWAS has shown an association between FHL2 variants rs1401209, rs9789507, rs7563316, rs17030964, rs4851776, rs2139109, and rs12997792 and acute myeloid leukemia." (PMID 34685595, 2021).
Alzheimer disease (3 papers, 2021 to 2024). A progressive, neurodegenerative disease characterized by loss of function and death of nerve cells in several areas of the brain leading to loss of cognitive function such as memory and language. "Finally, the FHL2 (where cg06639320 is mapped to) was described as potentially associated with Alzheimer’s disease, with its deficiency leading to neuronal migration delay and premature astrocyte differentiation." (PMID 39060467, 2024).
Arrhythmia (3 papers, 2023 to 2026). Any cardiac rhythm other than the normal sinus rhythm. "Together, these findings establish a mechanistic role for TTNmvs in AF pathogenesis and highlight IKs and FHL2 as potential therapeutic targets for TTN-related arrhythmias." (PMID 39677424, 2025).
fibrosis (3 papers, 2013 to 2020). the formation of excess fibrous connective tissue in an organ or tissue in a reparative or reactive process. "In Fhl2-deficient (Fhl2-ko) mice, BDL caused a more severe portal and parenchymal inflammation, extended portal fibrosis, higher serum transaminase levels, and higher pro-inflammatory and pro-fibrogenic gene expression compared to wild type (wt) mice." (PMID 31963815, 2020).
glioma (3 papers, 2013 to 2021). A benign or malignant brain and spinal cord tumor that arises from glial cells (astrocytes, oligodendrocytes, ependymal cells). "Except for the genes of FHL2 and YTHDF3, there were significant differential expression of the other genes between WHO grade II and WHO grade III glioma." (PMID 33264518, 2021). "FHL2 interacts with EGFR and EGFRvIII to increase their levels and promotes glioma growth." (PMID 33987093, 2021).
liver cancer (3 papers, 2014 to 2017). An epithelial or non-epithelial malignant neoplasm that arises from the liver. "Overexpression of FHL2 inhibits the growth of colon and liver cancer cell lines, whereas an opposite, growth-accelerating function has been associated with FHL2 based on experiments with fibroblasts of FHL2-KO mice." (PMID 24736599, 2014). "Additionally, FHL2 promotes activation of nuclear factor (NF)-κB in gastric cancer, liver regeneration, and liver cancer, and upregulated FHL2 expression in human liver samples is significantly associated with increased inflammatory response and liver cirrhosis." (PMID 28714941, 2017).
ovarian granulosa cell tumor (3 papers, 2016 to 2023). A granulosa-stromal cell tumor that arises from the ovary. "Our previous study showed that FHL2 is highly expressed in human ovarian granulosa cell tumors and epithelial tumor tissues and cells." (PMID 37015904, 2023). "We previously showed that ectopic expression of four and a half LIM domains 2 (FHL2) promoted ovarian granulosa cell tumor progression." (PMID 37015904, 2023). "Our previous study showed that FHL2 plays a critical role in the initiation and progression of ovarian granulosa cell tumor (GCT) via controlling AKT1 gene transcription." (PMID 33092075, 2020). "Our previous study showed that FHL2 plays a critical role in the initiation and progression of ovarian granulosa cell tumor via regulating AKT1 transcription." (PMID 33092075, 2020). "The aim of this study was to determine the role and functional mechanism of FHL2 in the progression of ovarian granulosa cell tumors (GCTs)." (PMID 27415427, 2016). "FHL2 is a promising target for the development of novel drugs against ovarian granulosa cell tumor." (PMID 27415427, 2016). "Therefore, FHL2 is a key regulator of GCT tumor cell survivor and GCT progression, and is also a very promising target for development of drugs against ovarian granulosa cell tumors." (PMID 27415427, 2016).
aortic stenosis (2 papers, 2014 to 2023). Aortic valve stenosis is a aortic valve disease caused by the incomplete opening of the aortic valve. "We then investigated the subcellular localization of FHL2 by immunogold labeling in cardiac myofibres on ultrathin sections of ventricular tissue obtained from of a human donor, a patient with aortic stenosis, two HCM patients with a MYBPC3 mutation, and from WT and Hom-KI mice." (PMID 25358972, 2014).
asthma (2 papers, 2022). "Activation of Fhl2 by recall allergen stimuli downregulated Bach2 and JunD and activated the ERK1/2-AP1 and STAT6 pathways, inducing a memory-driven asthma phenotype." (PMID 36524132, 2022). "FHL2, another FHL protein family member, serves as a new target for treating asthma, and silencing of FHL2 suppresses airway inflammation in OVA-induced asthmatic mice." (PMID 36184652, 2022).
atrial fibrillation (2 papers, 2017 to 2021). A disorder characterized by an electrocardiographic finding of a supraventricular arrhythmia characterized by the replacement of consistent P waves by rapid oscillations or fibrillatory waves that vary in size, shape and timing and are accompanied by an irregular ventricular response. "This extended gene network contained a number of transcription factors (Tbx5, Hand2, Fhl2, and Gata4) and ion/calcium handling genes (Ank2, Cacna2d2, Scn5a, Kcnd2, Kcnj5, Myoz2, Casq2, Csrp3, and Gja3) of interest in the context of atrial fibrillation." (PMID 28720711, 2017). "Interestingly, Fhl2 had one of the highest fold-changes in expression in the left atria of patients with atrial fibrillation compared to healthy controls, supporting a role for dysregulated TTN signaling in the pathobiology of atrial fibrillation." (PMID 28720711, 2017).
cholangiocarcinoma (2 papers, 2021 to 2025). A carcinoma that arises from the intrahepatic biliary tree (intrahepatic cholangiocarcinoma) or from the junction, or adjacent to the junction, of the right and left hepatic ducts (hilar cholangiocarcinoma). "Our in silico analysis revealed that a total of six TFs (SP1, CREB1, MAX, FHL2, RFX1 and HIF1A) were upregulated in cholangiocarcinoma tissues." (PMID 34199886, 2021). "Moreover, expressions of six TF genes (SP1, CREB1, MAX, FHL2, RFX1, and HIF1A) was positively correlated with the expression of ITGA6 and ITGB1 in cholangiocarcinoma tissues." (PMID 34199886, 2021).
cholestasis (2 papers, 2020 to 2022). Impairment of the bile flow caused by obstruction within the liver, or outside the liver in the bile duct system. "The expression of FHL2 suppresses NTCP activity, and FHL2 deficiency aggravates cholestasis in mice." (PMID 36678658, 2022). "Together, these data indicate that the elevated synthesis and uptake of bile acids in FHL2-depleted cells may be a potential cause for enhanced hepatocellular injury in cholestasis." (PMID 31963815, 2020).
chronic kidney disease (2 papers, 2024). Impairment of the renal function secondary to chronic kidney damage persisting for three or more months. "Given the regulatory effect of FHL2 on activities of both signaling, inappropriate prolonged overexpression of FHL2 may impel the conversion of AKI to chronic kidney disease (CKD)." (PMID 38814462, 2024).
dilated cardiomyopathy (2 papers, 2019 to 2021). Cardiomyopathy which is characterized by dilation and contractile dysfunction of the left and right ventricles. "The Ventricles-Enriched MYH7, FHL2, TNNC1 and TNNI3 genes were associated with dilated cardiomyopathy (DCM)." (PMID 34088950, 2021). "Of note, several iPTGs, such as ACTA2, FHL2, PARD6B, and SLC30A1, may be linked to iASPP-related phenotypes such as sudden cardiac death and dilated cardiomyopathy." (PMID 31395738, 2019).
hyperferritinemia (2 papers, 2012 to 2025). "Diagnostic work-up confirmed FHL2 redirecting interpretation of the initial episode (fever, weight loss, weakness, hepatosplenomegaly, pancytopenia, hypertriglyceridemia, hypofibrinogenemia, hyperferritinemia, with polyclonal T-cell lymphoproliferation)." (PMID 22970278, 2012).
hypertensive nephropathy (2 papers, 2019). Kidney damage that results from chronically elevated blood pressure; complications include glomerular damage resulting in proteinuria and hematuria. "As Rac1 activation is the common pathway of podocyte effacement, FHL2 inhibition therefore should be effective not only in hypertensive nephropathy but also in other glomerular diseases." (PMID 31040292, 2019). "Here, we used micro-dissected human kidney samples, in vitro podocyte culture experiments, and a hypertension animal model to determine the possible role of FHL2 in hypertensive nephropathy." (PMID 31040292, 2019). "In this current study, we reported FHL2 is an important mediator in hypertensive nephropathy." (PMID 31040292, 2019).
leukemia (2 papers, 2017 to 2021). A malignant (clonal) hematologic disorder, involving hematopoietic stem cells and characterized by the presence of primitive or atypical myeloid or lymphoid cells in the bone marrow and the blood. "FHL2 is often encountered in the context of oncology, and a large body of research implicates FHL2 in the development of leukemia." (PMID 34685595, 2021). "Several of these studies showed that increased FHL2 expression correlates with poor prognosis of leukemia." (PMID 34685595, 2021). "Immunofluorescence analysis further demonstrated the interaction between FHL2 and iASPP, and both of them localized in nucleus and cytoplasm in leukemia cells." (PMID 28402264, 2017). "According to the biological changes of leukemia cells after FHL2 or iASPP knockdown, the expression level of cell cycle regulators and Bcl-2 family members were analyzed by Western blot assay." (PMID 28402264, 2017). "That FHL2 highly expressed in some leukemia cell lines, FHL2 knockdown experiment was performed to address its role in leukemogenesis." (PMID 28402264, 2017). "Above results indicated that silence of either FHL2 or iASPP expression had a similar effect on leukemia cells, which suggested that both of them might play an important role in leukemogenesis." (PMID 28402264, 2017). "We had confirmed that iASPP interacted with FHL2, and knockdown of FHL2 expression could play a role on cell proliferation, cell cycle and cell apoptosis in leukemia cells." (PMID 28402264, 2017). "The results may help to understand the role of FHL2 and iASPP interaction in leukemia cells, and provide a novel therapeutic target for AML." (PMID 28402264, 2017). "The results indicated that both iASPP and FHL2 highly expressed in some leukemia cell lines, when silenced either FHL2 or iASPP could reduce the cell proliferation, induce cell cycle arrest at G0/G1 phase, and increase cell apoptosis via p21 and Bcl-2 signaling pathways." (PMID 28402264, 2017). "High expression of iASPP in leukemia cells could inhibit cell apoptosis and promote cell proliferation, then we wanted to address whether this effect was dependent on the interaction of FHL2, and down-regulated the expression of iASPP would affect that of the other and vise verse?" (PMID 28402264, 2017).
lymph node metastasis (2 papers, 2016 to 2025). "Univariate analysis demonstrated that tumor stage, lymph node metastasis (p = 0.041), and FHL2 level (p = 0.012) were significantly associated with OS." (PMID 40482916, 2025). "Similarly, tumor stage, lymph node metastasis (p = 0.009), and FHL2 level (p = 0.015) showed significant associations with DFS." (PMID 40482916, 2025). "The co-expression of FOXK1 and FHL2 was significantly correlated with differentiation and lymph node metastasis." (PMID 27892920, 2016). "Patients with larger tumors (>3 cm) or lymph node metastasis exhibited significantly higher FHL2 levels compared to those with smaller tumors or no metastasis." (PMID 40482916, 2025). "In addition, patients with larger tumors (>3 cm) or lymph node metastasis displayed significantly higher FHL2 levels compared to those with smaller tumors or no metastasis." (PMID 40482916, 2025).
melanoma (2 papers, 2015 to 2025). A malignant, usually aggressive tumor composed of atypical, neoplastic melanocytes. "Using this model system, we identified the mechanosensory gene FHL2 as one early sensor of changes in the ECM and suggest a FHL2-p21/AP-1 axis contributing to the dormant phenotype of melanoma cells in CIB." (PMID 40206148, 2025). "In melanoma cells, however, the synergistic overexpression of SKI and FHL2 enhanced cell growth." (PMID 26320172, 2015).
neuroblastoma (2 papers, 2017 to 2022). Neuroblastoma (NB) is the most common solid, extracranial childhood tumor. "After retinoic acid induced differentiation of neuroblastoma cells, FHL2 expression increases and counteracts the inhibitory effects of the Id proteins on E47, resulting in restored E47 induced transcription." (PMID 28122577, 2017). "Therefore, FHL2 is proposed to be a repressor of the oncogenic activity of Id2 in neuroblastoma." (PMID 28122577, 2017).
renal fibrosis (2 papers, 2018 to 2021). A final common manifestation of a wide variety of chronic kidney diseases characterized by glomerulosclerosis and tubulointerstitial fibrosis. "The likely mechanism is that FHL2 is a potent activator of the Wnt/β-catenin and TGFβ/β-catenin pathways (major drivers of renal fibrosis), and accordingly its absence abrogates the nuclear accumulation and activity of β-catenin." (PMID 34204945, 2021). "And the regulatory correlation between FHL2 and β‐catenin and its potential role in tubular EMT and renal fibrosis remain unknown too." (PMID 29193729, 2018). "Importantly, fibroblast-specific deletion of FHL2 attenuated myofibroblast accumulation (α-SMA expression) and matrix deposition (collagen, fibronectin) in the unilateral ureteral obstruction (UUO) model of renal fibrosis." (PMID 34204945, 2021).
sarcoma (2 papers, 2022 to 2025). A usually aggressive malignant neoplasm of the soft tissue or bone. "In contrast, patients with elevated FHL2 expression exhibited favorable OS in LIHC, sarcoma (SARC), UCEC, thymoma (THYM), and PCPG." (PMID 40482916, 2025).
type 2 diabetes (2 papers, 2018 to 2022). "Given that FHL2 expression in humans increases with age and that high expression levels of FHL2 are associated with beta cell dysfunction, we propose that enhanced FHL2 expression in elderly individuals contributes to glucose intolerance and the development of type 2 diabetes." (PMID 35802167, 2022). "In this study, we determined that in transcriptome datasets of human pancreatic islets FHL2 expression is higher in individuals with increased HbA1c values, as well as in those with type 2 diabetes." (PMID 35802167, 2022). "In recent EWASs, around 60% of the methylation changes associated with age in pancreatic islets also occur in blood, including FHL2, KLF14, FAM123C and GNPNAT1, all genes known to be associated with type 2 diabetes or insulin secretion." (PMID 29164275, 2018). "In dataset GSE76894, the FHL2 expression level was higher in individuals diagnosed with type 2 diabetes than in the non-diabetic individuals." (PMID 35802167, 2022). "Finally, an overall insulin secretion pathway signature score was calculated for each of the low- and high-HbA1c (or non-diabetic and type 2 diabetes) samples and the score was plotted against FHL2 expression." (PMID 35802167, 2022).
acute erythroid leukemia (1 paper, 2017). An acute myeloid leukemia characterized by a predominant immature erythroid population. "It is notable that FHL2 also highly expressed in acute erythroid leukemia (AML-M6), indicating that FHL2 may play a vital role in leukemogenesis, especially in the type of AML-M6." (PMID 28402264, 2017).